APLN (apelin)
Diseases named in the same sentence as APLN in open-access papers (continued):
Sharing a sentence is not in itself a finding about the gene and the disease.
fibrosis (14 papers, 2011 to 2023). the formation of excess fibrous connective tissue in an organ or tissue in a reparative or reactive process. "Since serum apelin is elevated only after vascular damage induced by cirrhosis development, reversal of cirrhosis associated fibrosis and hepatic damage would be the driving factors for decreasing serum apelin and counteracting apelin-induced PH." (PMID 35831335, 2022). "•Previous studies of fibrosis and cirrhosis patients reported variable plasma concentrations of apelin ranging from 200 pg/ml to 10,000 pg/ml." (PMID 33171278, 2021). "There was a significant reduction in apelin levels in patients with both fibrosis (6.5 ± 0.6 pg/ml) and cirrhosis (8.3 ± 1.2 pg/ml) compared to healthy controls (15.4 ± 2.0 pg/ml)." (PMID 33171278, 2021). "A study examining a group of patients with non-alcoholic fatty liver disease (NAFLD) with early fibrosis reported higher levels of apelin-36 in sera within the disease group." (PMID 33171278, 2021). "•Using solid-phase extraction, we report decreased plasma levels of apelin in fibrosis and cirrhosis patients compared to healthy volunteers." (PMID 33171278, 2021). "Apelin was significantly reduced in plasma of patients with both early (fibrosis) and late-stage (cirrhosis) liver disease." (PMID 33171278, 2021). "Our results show, using a validated assay system with solid-phase extraction to reduce interference, apelin immunoreactive levels are reduced in patients with fibrosis and cirrhosis." (PMID 33171278, 2021). "Apelin improved mechanical efficiency, at least in part, due to the inhibiting cardiac fibrosis and apoptosis in the LV myocardium, reducing collagen deposition in the aorta and dilating the resistant artery." (PMID 31316680, 2019). "Apelin improved mechanoenergetics, at least in part, due to its inhibiting cardiac fibrosis and apoptosis in LV myocardium, reducing collagen deposition in the aorta and dilating the resistant artery." (PMID 31316680, 2019). "In contrast to NAFLD models, the present study shows that serum apelin level is elevated in patients with either fibrosis or cirrhosis due to HCV, with significant differences among the two groups being higher in the latter, even after apelin adjustment." (PMID 22007137, 2011). "In this setting, we also found apelin serum level to be significantly elevated in patients with fibrosis." (PMID 22007137, 2011). "The results showed that glomerular fibrosis and expression of α-SMA and fibronectin in podocytes of STZ-treated β5iKO mice were decreased compared to STZ-treated C57/BL mice, and apelin could not alleviate the glomerular fibrosis and expression of α-SMA and fibronectin in STZ-treated β5iKO mice." (PMID 30301930, 2018). "As previously reported, unlike apelin, levels of BMP9 and pBMP10 are not significantly reduced in patients with fibrosis compared to healthy controls (BMP9, 218.1 ± 9.5 vs 315.6 ± 24.7 pg/ml, p>0.05; pBMP10, 3479.6 ± 298.3 vs 2909.2 ± 458.2 pg/ml, p > 0.05)." (PMID 33171278, 2021). "However, our correlation was quite significant in ASC but was unexpectedly nonsignificant in the case of progressive stages of fibrosis and cirrhosis, suggesting that the upset of the apelin system in these stages may follow a unique different pattern irrelevant to IR." (PMID 22007137, 2011). "Serum apelin levels were significantly higher in patients with CHC with median value (3.25) when compared with controls (1.11), at P < 0.0001, with significant apelin variations among asymptomatic carriers (ASC), fibrosis, and cirrhosis patients, and also among obese and nonobese patients." (PMID 22007137, 2011).
liver disease (14 papers, 2011 to 2025). "Two studies reported increased circulating levels of apelin in patients with cirrhosis, with one of the studies reporting the highest levels in patients with the most severe liver disease." (PMID 33171278, 2021). "Owing to the variability in the reported levels of apelin peptides in liver disease patients, we have used this method to extract apelin from plasma samples from the same cohort in which BMP9 and BMP10 were measured and quantified apelin levels by ELISA." (PMID 33171278, 2021). "A limited number of studies have measured apelin levels in the plasma of patients with liver disease, including cirrhosis, but correlations between disease state and peptide concentration have been variable." (PMID 33171278, 2021). "Our results suggest that apelin signalling pathway is reduced in fibrosis, an early stage in the development of liver disease." (PMID 33171278, 2021). "The precise role of apelin in the pathophysiology of liver disease in general and fibrosis, in particular, is unclear." (PMID 33171278, 2021). "Patients with advanced liver disease show high circulating levels of both endocannabinoids and apelin, and their respective signalling pathways appear to be upregulated in advanced liver disease." (PMID 31653030, 2019). "Recent studies have reported multiple roles for the apelin/APJ system in liver disease, including acute liver injury, regeneration, fibrosis progression, and cirrhosis." (PMID 31653030, 2019). "Some studies reported that the level of serum apelin was increased in some liver diseases, such as NAFLD and cirrhosis." (PMID 31270645, 2019). "Further experimental or clinical findings will help to determine the potential of therapeutic strategies targeting the apelin/APJ system for the treatment of liver disease." (PMID 31653030, 2019). "Apelin, the endogenous ligand of angiotensin-like-receptor 1, is an emergent peptide involved in liver disease." (PMID 29535774, 2018). "Apelin was involved in regulating fibrogenic activity induced by angiotensin II and endothelin-1, and apelin would be an essential regulator of fibrogenesis in human liver disease." (PMID 29340118, 2017). "The validation of using apelin/APJ as a biomarker in different liver diseases would also be a crucial step toward its clinical use." (PMID 28484393, 2017). "In this review, we summarize the latest studies on the functions of the apelin/APJ system in liver disease." (PMID 28484393, 2017). "Recent studies have reported there are multiple roles for the apelin/APJ system in liver disease, including acute liver injury, liver regeneration, formation of cirrhotic liver and fibrosis progression." (PMID 28484393, 2017). "More recently, the inhibition of apelin with pharmacology blockader (F13A) increased liver regeneration after hepatectomy, strengthening the potential importance of apelin in liver diseases." (PMID 25918733, 2015). "HCV-related disease progression was associated with greater median values of apelin compared to nondiseased control patients, while those with cirrhosis had the highest apelin concentrations among those with liver disease, with median value (3.9)." (PMID 22007137, 2011). "In summary, these results suggest that apelin exacerbates liver disease in MASH mice." (PMID 39744169, 2025). "However, we have found that the decrease in plasma apelin occurs at an earlier stage of liver disease than for BMP9 and BMP10 suggesting that if BMPR-II signalling is impaired this is not mediated via loss of these receptor ligands." (PMID 33171278, 2021). "In contrast, the scenario and role of the apelin system are completely different in liver disease." (PMID 31653030, 2019). "Additionally, some studies have reported that serum levels of apelin were increased in some liver diseases, such as nonalcoholic fatty liver disease and cirrhosis." (PMID 31687083, 2019). "However, the mechanism of the upregulation of apelin expression in liver disease was still under investigation." (PMID 31687083, 2019).
liver disease (continued). "Also, further experimental or clinical findings will help to determine the potential of therapeutic strategies targeting the apelin/APJ system for treatment of liver disease." (PMID 28484393, 2017). "Additionally, apelin levels were significantly correlated with the severity of liver disease in patients with alcoholic cirrhosis." (PMID 29340118, 2017). "In this review, we summarize the role of the apelin/APJ system in liver disease." (PMID 28484393, 2017). "Thus, this study aims to address if there is relation between apelin serum levels and liver disease progression in a previously characterized cohort of established CHC Egyptian patients." (PMID 22007137, 2011). "Thus, apelin emerges as a major contributor to the fibrogenic process(es) occurring in liver disease as well as playing role in disease progression." (PMID 22007137, 2011). "Apelin has been shown to increase the synthesis of collagen I and platelet-derived growth factor receptor β (PDGFRβ) in LX-2 cells, indicating that apelin may be an important mediator of fibrosis in human liver disease." (PMID 39744169, 2025). "However, it remains unclear whether apelin signalling is detrimental in liver disease or is beneficial and therefore, whether an apelin antagonist or agonist have clinical use." (PMID 33171278, 2021). "However, the biological function of apelin in liver disease is still ongoing." (PMID 31687083, 2019). "Apelin/APJ system may act as a novel potential therapeutic target for liver disease." (PMID 29340118, 2017). "Tiani and his coworkers suggested that the expression of endogenous apelin/APJ signaling is associated with development of portal hypertension and contributes to the formation of portosystemic collateral blood vessels and splanchnic neovascularization in portal hypertensive rats." (PMID 22007137, 2011). "Therefore, highlighting the apelin system would present a new therapeutic target for liver disease." (PMID 22007137, 2011). "Additionally, apelin is more elevated in patients with ascites and portal hypertension and may have role in the development of these complications." (PMID 22007137, 2011). "Apelin and its receptor angiotensin II receptor like-1 (APJ receptor) appear to be involved in liver diseases including fibrosis and cirrhosis." (PMID 37670786, 2023). "The apelin/APJ system is a critical regulator of various physiological functions, such as glycometabolism, liver disease and macrophage activation." (PMID 36291151, 2022). "The expression of APLN and its receptor APJ comprises a system that acts as a critical regulator of various physiological functions, such as glycometabolism, liver disease, and macrophage activation." (PMID 32131466, 2020). "The APLN/APJ system is a critical regulator of various physiological functions, such as glycometabolism, liver disease and macrophage activation." (PMID 32420902, 2020). "However, whether apelin/APJ has important functions in liver disease is still under investigation." (PMID 28484393, 2017). "Coinciding with that line, our study also demonstrated that obese subjects with CHC had significant increased circulating apelin levels than lean patients, regardless of the stage or grade of liver disease." (PMID 22007137, 2011).
chronic heart failure (13 papers, 2015 to 2023). "Plasma concentrations of the novel peptide apelin are decreased in patients with chronic heart failure." (PMID 34076064, 2021). "Therefore, drugs targeting apelin/APJ system undoubtedly provide more therapeutic options for patients with congestive heart failure accompanied with hyponatremia." (PMID 33679444, 2021). "More interestingly, acute administration of apelin in patients with chronic heart failure could increase cardiac output and left ventricular performance." (PMID 25993436, 2015). "Indeed, acute administration of apelin restores cardiovascular functions in chronic heart failure." (PMID 31653030, 2019).
diabetic cardiomyopathy (13 papers, 2008 to 2025). Diabetic cardiomyopathy is a disorder of the heart muscle in people with diabetes. "KEGG pathway analysis showed that the target genes of miR-99a-5p were associated with: apelin signaling pathway, HIF-1 signaling pathway, diabetic cardiomyopathy, EGFR tyrosine kinase inhibitor resistance, and thermogenesis." (PMID 36992332, 2023). "Due to the inotropic properties and vasodilation induced by apelin, plasma apelin enhancement appears to be a compensatory mechanism for maintaining cardiac output in rats with hypertensive overload or diabetic cardiomyopathy." (PMID 36093083, 2022). "SIRT3, a member of sirtuins family, is considered an essential transcription factor in the apelin-induced protection of diabetic cardiomyopathy." (PMID 35355561, 2022). "A study has also shown that apelin therapy can increase capillary density to improve diabetic cardiomyopathy." (PMID 36465455, 2022). "Apelin gene therapy increases myocardial vascular density and ameliorates diabetic cardiomyopathy via upregulation of sirtuin." (PMID 26342945, 2015). "In subsequent studies, we demonstrated that overexpression of apelin improved myocardial capillary density and alleviated diabetic cardiomyopathy via SIRT3 up-regulation in db/db mice." (PMID 25782072, 2015). "The differentially expressed genes between the cardiomyocytesCSDC2 high subset and the cardiomyocytesCSDC2 low subset were mainly concentrated in processes related to myocardial remodeling, such as Cytoskeleton in muscle cells, Mitophagy—animal, Apelin signaling pathway, and Diabetic cardiomyopathy." (PMID 40933310, 2025). "In addition, APLN gene therapy can promote angiogenesis and improve the recovery of cardiac function in diabetic cardiomyopathy by up-regulating SIRT3 pathway." (PMID 35002528, 2022). "These raised a possibility that apelin might be related to the endothelial injuries and microvascular dysfunction in diabetic cardiomyopathy." (PMID 33504680, 2021). "Therefore endothelial specific APJ knockout mice were adopted to detect the effects of apelin on diabetic cardiomyopathy." (PMID 33504680, 2021). "Though not well understood, the altered expression of apelin we observed in the diabetic heart in response to rosiglitazone may present a novel pathway for the study of diabetic cardiomyopathy." (PMID 18648539, 2008). "Previous studies showed that apelin increases SIRT3 expression, improves cardiac function, and ameliorates diabetic cardiomyopathy." (PMID 35355561, 2022). "Our previous study shows that apelin (APLN) increases Sirtuin 3 (Sirt3) expression and ameliorates diabetic cardiomyopathy." (PMID 25311234, 2015).
Hyperglycemia (13 papers, 2015 to 2025). An increased concentration of glucose in the blood. "Recent research has highlighted the significant role of continuous apelin infusion in improving serum insulin levels and reducing hyperglycemia in rats with T2DM induced by a high-fat diet and STZ." (PMID 38622732, 2024). "We observed that MSC-derived sEVs, specifically those from WJ-MSCs overexpressing apelin, effectively enhance insulin sensitivity, increase glucose uptake in peripheral tissues, and inhibit hyperglycemia and β-cell apoptosis." (PMID 38622732, 2024). "Taken together, our data suggest that Pyr-apelin-13 delivery circumvents the resistance mechanism induced by hyperglycemia, providing an effective angiogenic response under hypoxic conditions." (PMID 37636297, 2023). "In conclusion, our comprehensive single-cell RNA sequencing data of testes from diabetic patients uncovers an important role of APLN/APJ in regulating BTB function under hyperglycemia conditions." (PMID 36443325, 2022). "Our work lent support to a contributory role for the apelin-APJ pathway to hyperglycaemia from a genetic standpoint." (PMID 31217908, 2019). "In conclusion, these findings offered evidence for the gender-specific involvement of the apelin-APJ system in predisposition to MetS and hyperglycaemia and set the stage for novel diagnostic methods and therapeutic approaches for MetS and hyperglycaemia." (PMID 31217908, 2019). "Considering the complexity of animal models, NRCMs under high glucose (30 mM, mimic of hyperglycemia) were utilized to investigate the effect of apelin on Cx43 expression in the present study." (PMID 29392082, 2018). "In summary, this study shed new light on the potential role of apelin in protecting the cardiac gap junctions from remodeling under hyperglycemia." (PMID 29392082, 2018). "In addition, exercise is able to reverse the low cardiac apelin and APJ expression caused by hyperglycemia." (PMID 40003929, 2025). "The signaling pathways by which apelin may promote angiogenesis under hyperglycemia were investigated in the ischemic adductor muscle." (PMID 37636297, 2023). "Furthermore, apelin reduces caspase-3 activity and abolishes the pro-apoptotic effect of high glucose in hyperglycaemia, suggesting the therapeutic effect of apelin in DKD." (PMID 36611944, 2022). "In this study, we demonstrated that icv injection of high levels of apelin, similar to that observed in the hypothalamus of obese/diabetic mice, in normal mice, induces a diabetic phenotype with fasting hyperglycemia, fasting hyperinsulinemia and glucose intolerance." (PMID 25759638, 2015). "To directly define the link between high glucose and APLN expression, we adapted a mouse Sertoli cell line TM451 to mimic the microenvironment of BTB under hyperglycemia conditions." (PMID 36443325, 2022). "Our study demonstrated that, unlike VEGFR signaling pathways, the apelin/APJ pathways are not affected by hyperglycemia, making the apelinergic system a potential target for angiogenic therapy." (PMID 37636297, 2023). "Production of hypothalamic H2O2 seems to have a mitochondrial origin, since icv injection of DPI 30 min before apelin treatment does not inhibit fasting hyperglycemia." (PMID 25759638, 2015).
left ventricular hypertrophy (13 papers, 2014 to 2025). Enlargement of the LEFT VENTRICLE of the heart. "The level of apelin-36 was measured in patients and rats with left ventricular hypertrophy." (PMID 29875677, 2018). "Therefore, as predicted, exogenous apelin is beneficial in a range of animal HF models, and retained or enhanced the inotropic action of apelin and attenuated left ventricular hypertrophy." (PMID 26143239, 2015). "However, if serum apelin affect the left ventricular hypertrophy (LVH) prevalence in hypertensive patients remains unknown." (PMID 26342945, 2015). "This means that apelin/APJ expression decreases in the myocardium, while plasma apelin increases in left ventricular hypertrophy." (PMID 36093083, 2022). "In humans, there are data suggesting a strong negative correlation between serum apelin levels and left ventricular hypertrophy." (PMID 35207580, 2022). "In addition, through the regulation of the apelin/APJ system, puerarin exerts protective effects on the development of left ventricular hypertrophy by renal hypertension." (PMID 30987658, 2019). "However, hypertensive patients with left ventricular hypertrophy were shown to exhibit reduced plasma apelin levels when compared to hypertensive subjects without left ventricular hypertrophy." (PMID 41515891, 2025). "Second, apelin has been shown to increase myocardial contractility by enhancing the sensitivity of myofilaments to activator Ca2+, leading to augmentation of cardiac output but without developing left ventricular hypertrophy." (PMID 35847238, 2022).